WIZ (WIZ zinc finger)
Description:
May link EHMT1 and EHMT2 histone methyltransferases to the CTBP corepressor machinery. May be involved in EHMT1-EHMT2 heterodimer formation and stabilization (By similarity).
Synonyms: ZNF803
Tractability: Small molecule: a structure with a bound ligand is known; a high-quality ligand is known. PROTAC: UniProt records ubiquitination sites on it; ubiquitination databases record sites on it; its protein half-life has been measured; a small molecule that binds it is known.
Gene: Protein-coding gene on chromosome 19 (15,419,978 to 15,449,975, reverse strand). Ensembl gene ENSG00000011451.
Subcellular location: Nucleus
Subcellular location (Human Protein Atlas): Nucleoplasm
Gene Ontology:
Molecular function: DNA-binding transcription factor activity, RNA polymerase II-specific; histone methyltransferase binding; protein binding; protein-containing complex binding; RNA polymerase II cis-regulatory region sequence-specific DNA binding; transcription corepressor binding
Biological process: positive regulation of nuclear cell cycle DNA replication; protein stabilization; regulation of transcription by RNA polymerase II
Cellular component: extracellular exosome; nucleoplasm; nucleus
Genetic constraint (gnomAD): Loss-of-function variants: 25 observed, 120.57 expected, observed/expected ratio (o/e) 0.21, 90% interval 0.15 to 0.29. The upper end of that interval is the gene's LOEUF score, 0.29, which puts it in group 1 of 6, group 1 being the genes least tolerant of losing a copy. Missense variants: 2,230 observed, 2,522.3 expected, observed/expected ratio (o/e) 0.88, 90% interval 0.85 to 0.92. Synonymous variants: 1,125 observed, 1,105.3 expected, observed/expected ratio (o/e) 1.02, 90% interval 0.97 to 1.07.
Homologues: Orthologues: dog WIZ (91% identical), pig WIZ (90% identical), rat Wiz (85% identical), rabbit WIZ (84% identical), mouse Wiz (75% identical), chimpanzee WIZ (51% identical), macaque WIZ (51% identical), tropical clawed frog wiz (38% identical), zebrafish wizb (31% identical), zebrafish wiza (15% identical). Paralogues in human: ZNF407 (8% identical), ZKSCAN7 (8% identical), ZNF287 (7% identical), ZNF852 (7% identical), ZBTB17 (7% identical), ZNF17 (7% identical), ZNF426 (7% identical), ZNF527 (7% identical), ZNF214 (7% identical), ZNF333 (7% identical), ZNF34 (7% identical), ZNF416 (7% identical), and 38 more.
Diseases named in the same sentence as WIZ in open-access papers:
WIZ is named in the same sentence as 8 diseases in open-access papers, as found by Europe PMC text mining. Sharing a sentence is not in itself a finding about the gene and the disease. The quoted sentences say what the papers report.
atherosclerosis (1 paper, 2020). A disease characterized by the build-up of fatty material and calcium deposition in the arterial wall resulting in partial or complete occlusion of the arterial lumen. "Lastly, WIZ and UNC45A were found to be the two DEGs mostly associated with two atherosclerosis subtypes." (PMID 33381146, 2020).
hepatocellular carcinoma (1 paper, 2025). A malignant tumor that arises from hepatocytes. "It encodes the WIZ, a zinc finger protein which is important for craniofacial development and is upregulated in hepatocellular carcinoma." (PMID 40572705, 2025).
renal tumors (1 paper, 2017). "Specifically, the transcript expressions of AKR1C1, S100A2, PLAU, SLC3A2, TBC1D2, and WIZ were decreased, while expressions of TGM2, SLC7A5, and NMI were increased in renal tumors when compared with non-tumorous control samples." (PMID 29272308, 2017).
sickle cell anemia (1 paper, 2025). "The action of the molecular glue leads to the degradation of the transcriptional repressor protein WIZ, thereby activating HbF expression and providing a therapeutic effect for sickle cell anemia." (PMID 41267108, 2025).
brain disorder (1 paper, 2020). A disease affecting the brain or part of the brain.
neurological disorders (1 paper, 2016). "It is possible that heterozygosity for rare WIZ mutations in humans could influence neurological disorders that have a complex genetic aetiology." (PMID 27410475, 2016).
tumor (1 paper, 2025). "Consistent with the bioinformatic prediction, GTF3C1, NR1H3, NTHL1, SNX, TMEM132A and WIZ expressions were markedly upregulated in the tumor group relative to the normal group." (PMID 41573564, 2025).
WIZ also shares sentences with these, for which no sentence is quoted: autism (1 paper).